GRPR (gastrin releasing peptide receptor)
Diseases named in the same sentence as GRPR in open-access papers (continued):
Sharing a sentence is not in itself a finding about the gene and the disease.
tumor (continued). "Conversely, tumor uptake of the GRPR or NPY(Y1)R mono-specific targeted agents were lower, confirming the improved tumor uptake of the bispecific construct over the mono-targeted agents." (PMID 33986665, 2021). "Heterodimers targeting PSMA/GRPr, tumor uptake (1 h p.i.)expressed as (% ID/g) in PC-3, AR42J, LNCaP or PC-3 PIP xenografts (Mean value ± Std)." (PMID 34944875, 2021). "Prolonged retention in the tumor is an attractive quality for a theranostic GRPR-seeking radiolabeled probe, agonist, or antagonist, especially during radionuclide therapy." (PMID 34680243, 2021). "Radiolabeled GRPR antagonists, besides being safer for human use, have often shown higher tumor uptake and faster background clearance than agonists." (PMID 32731473, 2020). "The clearance GRPR radioantagonists, in contrast to agonists, turned out to be much faster from physiological tissues than from tumor sites." (PMID 32731473, 2020). "Satisfactory tumor-to-organ ratios generated high contrast images in PSMA/GRPR-positive tumors in murine model up to 72 h pi." (PMID 32630176, 2020). "The overexpression of tumor-specific receptors for peptides in human cancer cells, such as gastrin-releasing peptide receptor, natriuretic peptide receptor, and somatostatin receptor, has indicated the ideal molecular basis for targeted imaging and therapy." (PMID 33335885, 2020). "The uptake in the pancreas (GRPR-expressing tissue) and tumor were on the same level for both radiolabelled conjugates." (PMID 33081166, 2020). "GRPR antagonists have shown an advantage compared to agonists due to better tumor activity uptake and retention and fast clearance of the tracer from non-targeted tissue, along with a minimum of side effects." (PMID 33352838, 2020). "GRPR is overexpressed in various types of cancer cells, and the production of GRP together with GRPR overexpression result in autocrine tumor growth stimulation." (PMID 33396360, 2020). "A synthetic bombesin/gastrin-releasing peptide-receptor antagonist (RC-3095) was able to produce long-lasting tumor regressions in murine and human tumor models in vitro and in vivo." (PMID 32848750, 2020). "In agreement with the in vitro data, [64Cu]Cu-NOTA-PEG2-RM26 showed a tendency to higher uptake in the tumor (p = 0.7) and GRPR-expressing tissues (pancreas, small intestine, and stomach) at 3 h p.i. in comparison with [64Cu]Cu-NODAGA-PEG2-RM26." (PMID 33352838, 2020). "In conclusion, we herein report a successful conjugation of a GRPR antagonist and an albumin-binding domain that retained GRPR-targeting in vivo and, due to binding to albumin, resulted in a high and stable tumor uptake over several days." (PMID 33081166, 2020). "The promising in vitro cellular uptake of 67Ga/Gd-based bombesin containing particles was confirmed through biodistribution studies in tumor bearing mice, indicating their integrity and ability to target the GRPr." (PMID 31978954, 2020). "In all cases, tumor-to-background levels were favorable, including those in the GRPR-rich pancreas and the kidneys." (PMID 32731473, 2020). "RM2-PET not only showed better delineation of the gross tumor volume and distinct regions of PCa but also benefited from the information given by radiotracers targeting GRPR." (PMID 33335885, 2020). "By using agonistic Bn peptides, the desensitization mechanism of the GRPR can be exploited for an active drug shuttling into the tumor cells." (PMID 32733853, 2020). "Compared with the corresponding radiolabeled agonist, antagonists of GRPR without internalizing or activating it were able to recognize more binding sites than agonists and had an even better tumor uptake and retention in GRPR positive tumors." (PMID 33335885, 2020). "Based on the C-terminal 7–14 amino acids, the peptides for GRPR imaging showed tumor localization with high specificity." (PMID 33335885, 2020).
tumor (continued). "Ex vivo biodistribution and PET/CT images showed high accumulation in GRPR-expressing PC-3 tumors for both conjugates resulting in favorable tumor-to-background ratios." (PMID 33352838, 2020). "Integrin αvβ3 is overexpressed on invasively growing tumors during metastasis and angiogenesis, thus rendering heterobivalent peptide binding to both proteins in principle suitable for efficient synergistic targeting of every GRPR-positive tumor type." (PMID 32751666, 2020). "It displayed in vivo specificity toward GRPR and a 2-fold higher tumour uptake in athymic nude mice bearing PC3 xenografts due to its higher in vivo stability." (PMID 32781656, 2020). "Extending the biological half-life of the GRPR-targeting ligand is a way to minimize the number of injections and to prolong the bioavailability of the ligand for binding to tumor cells." (PMID 33081166, 2020). "In the effort to optimize tumor-targeting, several groups investigated the labeling of a GRPR antagonist with long-lived radionuclides." (PMID 33352838, 2020). "Beside expression in tumor tissue, GRPR is expressed in various healthy tissues, such as breast, pancreas, prostate, and lung." (PMID 31671763, 2019). "In vivo specificity of [125I]I-Tyr-PEG2-RM26 and [111In]In-DOTA-PEG2-RM26 binding to GRPR-expressing PC-3 in tumour xenografts was evaluated by saturation of receptors using a co-injection of non-labelled peptide (NOTA-PEG4-RM26) at 0.5 h after injection." (PMID 31382362, 2019). "The in vivo specificity study showed that uptake of both [125I]I-Tyr-PEG2-RM26 and [111In]In-DOTA-PEG2-RM26 in tumours and GRPR-expressing tissues was specific." (PMID 31382362, 2019). "Radiometal-labelled antagonistic bombesin analogues have demonstrated efficient targeting of GRPR-expressing tumours." (PMID 31382362, 2019). "It was also demonstrated that agonists rapidly down regulate GRPR (10-fold within 10 min) resulting in lower in vivo tumor activity uptake for agonists than for the antagonists." (PMID 31340483, 2019). "These PSMA/GRPR bi-ligands all showed specific PSMA and GRPR PCa tumor targeting in vitro and in vivo." (PMID 31671763, 2019). "It is clearly evident that in-situ NEP-inhibition is a direct and more effective strategy than structural intervention to improve tumor targeting in this pair of GRPR-radioantagonists." (PMID 30871262, 2019). "Motivated by this gap in the inventory of GRPR-directed radioligands we have expanded our research efforts to native human GRP sequences in order to explore their applicability in GRPR-targeted tumor diagnosis and therapy." (PMID 30897789, 2019). "In conclusion, the charge and structure of chelating moiety had a profound influence on tumor targeting and biodistribution profile of radiocobalt-labeled GRPR antagonist RM26." (PMID 31745219, 2019). "To prevent rapid leakage of activity from tumor cells after internalization we chose a GRPR antagonist." (PMID 31340483, 2019). "Promising GRPR-selective radioligands based on receptor antagonists have been developed and evaluated in animals and in human, showing excellent tumor targeting and pharmacokinetic profiles." (PMID 30897789, 2019). "Results also showed that significant uptake occurred in the GRPR-positive organs, including pancreas, intestine, and tumor; maximal tumor uptake was found at 30 min for all the compounds." (PMID 30887136, 2019). "It demonstrated high affinity and specificity towards GRPR providing an imaging of xenografts with high contrast, and it inhibited tumor growth when administered with lutetium-177." (PMID 31340483, 2019). "Recently a shift of paradigm has occurred toward radiolabeled GRPR-antagonists that, besides their higher inherent biosafety, have unexpectedly shown superior tumor targeting and faster background clearance from the body compared to agonists." (PMID 30871262, 2019). "Despite high tumor specificity, activation of GRPR triggers physiological responses and promotes tumor growth." (PMID 31340483, 2019).
tumor (continued). "The imaging of mice co-injected with excess PSMA- or GRPR-targeting monomers revealed the partial blocking of tumor uptake when only one monomer was co-injected and a pronounced blocking effect when both monomers were co-injected." (PMID 31540122, 2019). "An in vivo binding specificity 1 h pi of 111In-NOTA-DUPA-RM26 in PC3-PIP-xenografted mice demonstrated partially blockable tumor uptake when co-injected with an excess of PSMA- or GRPR-targeting agents." (PMID 31540122, 2019). "Biodistribution showed that uptake in pancreas and tumour was GRPR-specific for both radioconjugates." (PMID 31382362, 2019). "A novel and interesting approach would be the use of SB3 for pre-operative imaging and intra-operative radio-guided tumor detection of GRPR-expressing tumors, especially for the detection of GRPR-expressing metastases and non-palpable tumors." (PMID 29556947, 2018). "For this, we compared the in vivo stability and the biodistribution of [111In]SB3 without/with (−/+) PA, the latter by performing both biodistribution and SPECT/MRI studies in mice bearing GRPR-expressing PC-3 tumor xenografts." (PMID 29556947, 2018). "Next to tumor uptake, high radiotracer uptake was also observed in the GRPR-expressing pancreas and in the kidneys, the latter as a result of renal excretion and partial reabsorption of the radiopeptide." (PMID 29556947, 2018). "The compounds demonstrated high stabilities in human serum, hydrophilicities comparable to the monomeric lead peptides and high GRPR-mediated tumor cell uptakes in vitro." (PMID 29973529, 2018). "Gastrin-releasing peptide receptor antagonists have promise in theranostics of several highly incident tumours, including prostate and breast." (PMID 30543050, 2018). "It follows that the application of GRPR-targeting, radiolabelled bombesin analogues to the imaging and treatment of various neoplasms has raised considerable interest over the past 20 years." (PMID 30543050, 2018). "In favor of theragnostic perspectives, there was a significant reduction of uptake in the GRPR-rich mouse pancreas for both [68Ga]NeoBOMB1 and [177Lu]NeoBOMB1 with rapidly increasing tumor-to-pancreas ratios for the 200 pmol dose." (PMID 29137110, 2017). "Its widespread presence in many tumors and its intensive use in imaging approaches on the molecular level make the GRPR a very attractive marker for monitoring of the tumor therapeutic efficiency of hyperthermia." (PMID 28761146, 2017). "In mice bearing T-47D xenografts, [67Ga]NeoBOMB1 specifically localized in the tumor (8.68 ± 2.9% ID/g vs. 0.6 ± 0.1% ID/g during GRPR-blockade at 4 h pi)." (PMID 29137110, 2017). "Progress in this direction was facilitated by studies in preceding decades on GRPR-antagonist motifs developed by peptide chemists and applied with considerable success as anti-tumor agents in GRPR-positive xenografts in mice." (PMID 29137110, 2017). "Results from this study, revealed the high GRPR-affinity, unprecedented in vivo stability and prolonged retention of [67Ga]NeoBOMB1 in GRPR-positiveT-47D tumor models." (PMID 29137110, 2017). "One example is the preference for radiolabeled GRPR antagonist instead of agonists for tumor targeting, since it is similar to what was observed for SSTR radioligands, superior binding of GRPR antagonists vs. agonists was reported." (PMID 28134770, 2017). "Representative color-coded images illustrate the occurrence tumor fluorescence signals after hyperthermia treatments when optical probes targeting GRPR or αvβ3 integrin were applied." (PMID 28761146, 2017). "Further on, GRPR, αvβ3 integrin expression are versatile tools to surveil potential tumor regrow during therapy, beyond the conventional determination of tumor volumes." (PMID 28761146, 2017). "This can be assigned to a GPRR-specific process, given that during in vivo GRPR blockade at excess 40 nmol peptide dose uptake was banned in both pancreas (1.17 ± 0.11% ID/g; p < 0.001) and tumor (0.64 ± 0.10% ID/g; p < 0.001)." (PMID 29137110, 2017).
tumor (continued). "The goal of this study was to evaluate the tumor targeting properties of GRPR antagonist NOTA-PEG2-RM26 labeled with 55Co." (PMID 29097932, 2017). "The important aspect we have shown, for the first time, is that we can predict the three dimensional margins of the tumour based on GRPR expression, which is corroborated by CD44 staining." (PMID 27827443, 2016). "GRPR+ CD44+ cells in a group of two or three were scattered in the sections confirming the presence of tumour cells." (PMID 27827443, 2016). "The PC295 tumor used in this study showed promising morphological characteristics, with high tissue viability and high and homogenous GRPr expression, leading to an expected high accumulation of the targeting radiopeptide." (PMID 26769345, 2016). "Since the detection of metastatic tumour cells in the lymph nodes was difficult, serial sections were stained after a brief fixation, for GRPR and CD44 (an epithelial marker)." (PMID 27827443, 2016). "Both tumor regions exhibit increases in contrast enhancement from 30 minutes to 48 hours post injection of GRPR-targeted contrast agent, ProCA1.GRPR." (PMID 26577829, 2015). "Our results strongly demonstrate that ProCA1.GRPR is capable of semi-quantitatively evaluating GRPR expression levels between different tumor cells." (PMID 26577829, 2015). "Unlike these reported studies, our contrast agent enables the targeting of GRPR outside of tumor vessels with a brighter effect and improved in vivo pharmacokinetics." (PMID 26577829, 2015). "Its preferred receptor, gastrin-releasing peptide receptor (GRPR), is expressed by various cell types, including those of the gastric, respiratory, and nervous systems, and it is overexpressed in tumor cells." (PMID 25893195, 2015). "Consistent with results of the cultured cell studies, GRPR expression level in PC3 tumor tissue is significantly higher than that in H441 tumor tissue revealed by IHC staining." (PMID 26577829, 2015). "In the prostate, GRPR expression was also detected at high levels in the tumor precursor lesion high-grade prostatic intraepithelial neoplasia (HGPIN)." (PMID 26097883, 2015). "We also observed NIR fluorescence emission for both PC3 tumor and H441 tumors 48 hours post injection of ProCA1.GRPR." (PMID 26577829, 2015). "Intensity of immunofluorescence staining of ProCA1.GRPR in PC3 tumor tissue showed about 2-fold greater than that of H441 tumor tissues." (PMID 26577829, 2015). "The high relaxivity, improved in vivo biodistribubtion and pharmacokinetics enable in vivo imaging of GRPR in tumor bearing mice with a significantly reduced injection dose." (PMID 26577829, 2015). "ProCA1.GRPR is distributed in regions encompassing the entire tumor, and the agent clearly penetrates the tumor vessels as shown by CD31 staining." (PMID 26577829, 2015). "BBS and derivatives thereof are interesting vectors for the development of tumor targeting agents because of the overexpression of the GRPr by different tumor cells including prostate, breast, colon, and small-cell lung carcinomas." (PMID 23481882, 2013). "Lower ratios of tumor-to-blood and tumor-to-muscle in blocking experiments showed GRPR-dependant tumor uptake for both tracers." (PMID 22333272, 2012). "The expected advantages of multimeric compound are a higher uptake and retention of the peptide on GRPR-expressing tumor cells." (PMID 22333272, 2012). "18F-FB-BBN-RGD was also effective at imaging DU145 tumours with low GRPR levels, and showed reduced background signal compared to 18F-FB-RGD." (PMID 24213501, 2012). "While GRPR density on PC3 tumor cells is widely documented in vitro and in vivo, its expression is heterogeneous making it difficult to establish an average distance between the receptors." (PMID 22333272, 2012). "The agent showed low affinity for αvβ3in vitro, suggesting initial tumour binding occurs through GRPR, and binding of the RGD peptide facilitates subsequent tumour accumulation and retention and urinary excretion." (PMID 24213501, 2012).
tumor (continued). "Multimeric gastrin-releasing peptides are expected to have enhanced tumor uptake and affinity for GRPR." (PMID 22333272, 2012). "It is suggested that tumours should be biopsied to select patients for substance P-analogue trials based on the expression of the GRPR and another neuropeptide receptor." (PMID 12771999, 2003). "These tumour tissues highly expressed GRPR, as determined by immunochemical analysis." (PMID 41555955, 2026). "[177Lu]Lu-PKB2 and [177Lu]Lu-PKB3 demonstrated high in vivo specificity, as evidenced by the significant reduction in activity uptake in the tumor and GRPR-expressing organs (pancreas, stomach, and small intestines) after co-administration of an excess of NOTA-PEG2-RM26." (PMID 41231375, 2025). "Our cohort was predominantly male, with an imbalance between tumor and normal tissues, and heterogeneity in anatomic site, stage and treatment, which may have introduced variability into the GRPR prognostic analyses." (PMID 41266536, 2025). "Moreover, GRPR expression in these healthy tissues is at least one order of magnitude lower than in clinical tumor samples." (PMID 40775579, 2025). "Similarly, tissue uptake in GRPR-expressing regions was also reduced: tumor (5.4 ± 1%IA/g), pancreas (1.9 ± 0.1%IA/g), stomach (1.4 ± 0.2%IA/g), and small intestine (0.6 ± 0.1%IA/g)." (PMID 40775579, 2025). "Therefore, efforts have been made to develop GRPR antagonists for the diagnosis and treatment of GRPR-positive tumours." (PMID 39747850, 2025). "As a result, tumor-to-background ratios could be increased in the case of radiolabeled GRPR-antagonists." (PMID 41155959, 2025). "However, the blocking of GRPR resulted in a significantly reduced activity uptake both in the pancreas (4 ± 1% IA/g) and in tumours (1.3 ± 0.6% IA/g)." (PMID 40138074, 2025). "This parallel regulation underscores a broader role of hypoxia in modulating bombesin receptor family members, suggesting a potential role for GRPR in hypoxia-driven tumour cell survival and supporting its utility as a therapeutic target in anti-cancer strategies." (PMID 41226822, 2025). "The much higher uptake of [177Lu]Lu-AMBA in the pancreas than that in the PC-3 tumor xenograft might be due to its more selective binding to the mouse GRPR expressed on the mouse pancreas than the human GRPR expressed on PC-3 tumor xenografts." (PMID 40283887, 2025). "There was also a tendency for a higher uptake in some tissues (e.g. pancreas, tumor) for the [188Re]Re-labeled analogs in comparison with the ones labelled with Tc-99 m, especially for GRPR-expressing tissues, a trend also shown for PSMA and somatostatin analogs." (PMID 39825204, 2025). "GRPR-targeting peptides often have limited metabolic stability, which can compromise their clinical efficacy due to rapid degradation in the bloodstream, leading to reduced tumor uptake." (PMID 41231375, 2025). "Additionally, we compared DOTAGA and DOTA chelators to evaluate their impact on GRPR affinity and tumor retention in order to choose the optimal one in combination with Lu-177, aiming for use in TRT." (PMID 41231375, 2025). "The optimization of GRPR-targeted radiopharmaceuticals has extended to the development of multimeric constructs, offering an alternative strategy to enhance receptor binding and tumor accumulation." (PMID 41251982, 2025). "However, the absorbed dose of the clinical validated GRPR antagonist [177Lu]Lu-RM2 in the same tumor model was 429 mGy/MBq, which is 1.6-times that of [177Lu]Lu-LW02060." (PMID 40006047, 2025). "Furthermore, GRPR expression in primary HNSCC tumors has been associated with lymph node metastasis, extracapsular infiltration, and tumor progression." (PMID 41266536, 2025). "Since different biological processes regulate the expression of PSMA and GRPR, understanding the role of these two tumor biomarkers in patients with PCa could prove helpful for a better management of the disease." (PMID 40732291, 2025).